AR (androgen receptor)
Diseases named in the same sentence as AR in open-access papers (continued):
Sharing a sentence is not in itself a finding about the gene and the disease.
breast carcinoma (continued). "Therefore, we sought to investigate whether p68 and PDGFR-β co-regulate AR expression in breast cancer cells." (PMID 34659545, 2021). "It has been suggested that AR could be an emerging therapeutic target in breast cancer, especially tumors that are ER-negative, and scientific interest has been focused on the clinical significance of AR expression in ER-positive or triple-negative breast cancer." (PMID 34070921, 2021). "Thus, USP14 promotes resistance to enzalutamide in AR+ breast cancer." (PMID 34575114, 2021). "Therefore, USP14-targeted inhibition in combination with the enzalutamide AR antagonist might represent a potential therapeutic strategy for breast cancer therapy." (PMID 35069211, 2021). "However, consistent with our hypothesis, the results of GSEA using the androgen responsive gene set demonstrated that the expression of candidate genes accurately reflects a larger gene signature representing tumor AR activity in all breast cancer subtypes." (PMID 34736512, 2021). "Recent findings regarding the role of AR in breast cancer suggest that estimating AR activity may have clinical utility since trials with both Enzalutamide and Enobosarm showed efficacy in metastatic ER + disease resistant to other endocrine and chemotherapy treatments." (PMID 34736512, 2021). "Therefore, we further investigated AR expression in PDGFR-β knockdown breast cancer cells." (PMID 34659545, 2021). "Interestingly, expression of PDGFR-β in p68 knockdown breast cancer cells restored AR expression both in protein and mRNA levels, suggesting that p68 may regulate AR expression via PDGFR-β." (PMID 34659545, 2021). "Enzalutamide enhances the in vitro antitumor activity of trastuzumab in trastuzumab-resistant HER2+ cell lines, warranting clinical investigation of whether inhibiting AR in HER2+ breast cancers in combination with currently available anti-HER2 therapeutics could improve patient outcomes." (PMID 33591468, 2021). "The role of AR-signaling may be different among subtypes of breast cancer." (PMID 34392453, 2021). "More recently, pivotal findings into modulating the progesterone (PR) and androgen receptors (AR), with accompanying mechanistic insights into NR crosstalk and interactions with other proliferative pathways, have led to clinical trials in all of the major breast cancer subtypes." (PMID 34638457, 2021). "Thus, our results indicate that nuclear PDGFR-β regulates AR expression in breast cancer cells." (PMID 34659545, 2021). "Moreover, this indicated that ER could play a pivotal role in LAT1 regulation in breast cancer, as seen with AR in prostate cancer." (PMID 33436954, 2021). "In addition, miR-9-5p has been identified as a suppressor of AR expression in breast cancer." (PMID 34831421, 2021). "Thus, while AR agonists may be effective in luminal AR+ breast cancer, these data support the use of AR inhibitors for the treatment of TNBCs that express AR." (PMID 34680352, 2021). "Furthermore, AR is an independent predictor of survival for ERa+ breast cancers sufferers." (PMID 33266334, 2020). "AR staining was shown in a large clinical study to be associated with a relatively favorable outcome in ER positive patients while being a poor prognostic factor in ER negative breast cancer patients." (PMID 32230714, 2020). "Indeed, AR may play multiple roles in breast cancer, both in ER-positive (ER+) and ER-negative tumors, and these results have demonstrated that AR may be an effective target for the clinical treatment of patients with AR+ TNBC." (PMID 32117061, 2020). "In addition, the expression of AR and these microRNAs may depend on the expression of other receptors important for breast cancer control—PR, ER, and HER2." (PMID 32373367, 2020).
breast carcinoma (continued). "Other genes, such as ESR1 (logFC 6.02); GATA3 (logFC 3.88); ERBB4 (logFC 3.0); AR (logFC 2.94); CCDC170 (logFC 2.79); MAPT (logFC 2.45); PGR (logFC 2.91); PIP (logFC 5.42) in immunoglobulin G-binding protein from this cluster were closely associated with breast cancer progression." (PMID 32182819, 2020). "In addition, increased expression of NCOA3, with implications for AR activation, and variation in the length of the polyQ repeat in the NCOA3 gene have been associated with bone cancer, epithelial ovarian cancer, colorectal cancer, and breast cancer in humans." (PMID 32854182, 2020). "Therefore, AR expression may be an important target for directing treatments for patients with ER- breast cancer." (PMID 33062889, 2020). "Importantly, differences also exist in preclinical cell lines used to study AR+ breast cancers." (PMID 33062889, 2020). "There is not a clear association between AR signaling and breast cancer risk." (PMID 30975222, 2019). "Given the high frequency of AR expression in the majority of ERα-positive breast tumors, the AR/ERα crosstalk supports the intriguing idea of coupling androgen-based therapy with therapies targeting other important pathways, for the treatment of ERα-positive breast cancer patients." (PMID 31684907, 2019). "Moreover, it has been demonstrated that patients with breast cancer that express the androgen receptor tolerate enzalutamide well and benefit from enzalutamide treatment, suggesting enzalutamide has a significant antitumor effect and safety in AR positive breast cancer." (PMID 31126320, 2019). "Besides ER, PR and HER2, which promote the growth and progression of breast cancers, AR also may lead to the development of most breast cancers." (PMID 31126320, 2019). "However, this positivity rate is lower than that reported for primary breast cancer tissue, which raises the question whether the AR status of CTCs coincides with that of the primary tumour." (PMID 31718606, 2019). "The development of a validated AR gene expression signature or validated AR IHC threshold may enable clinicians to identify those patients with metastatic breast cancer who may benefit from AR targeted therapies, and for earlier stage disease, to aid in risk prognostication." (PMID 31840050, 2019). "By synergistically targeting AR-dependent and –independent pathways, this new combination treatment strategy may provide a potentially novel regimen for the treatment of AR-positive breast cancer in humans." (PMID 31126320, 2019). "However, no prior reported study has investigated whether USP14 inhibition in combination with AR antagonization has a benefit in treating breast cancer." (PMID 31126320, 2019). "We determined correlations between the gene expression of AR and a set of 79 selected genes which may be involved in the development of breast cancer, using the I-SPY 1, METABRIC, and TCGA datasets in the population as a whole, and in the triple negative (TN) cohorts of METABRIC and TCGA." (PMID 31840050, 2019). "The androgen receptor may characterize a discrete subtype of breast cancer." (PMID 31840050, 2019). "Importantly, AR may be considered as a target in the standard chemotherapeutic regimen for breast cancer." (PMID 31126320, 2019). "The androgen receptor (AR) may be expressed in breast cancer." (PMID 31840050, 2019). "A major hurdle in therapeutically targeting AR in breast cancer is that despite all the in vitro and clinical studies conducted we are still missing an essential part of the molecular landscape of breast cancer; that is, what dictates pro or anti tumorigenic responses to androgens." (PMID 30416486, 2018). "The literature on AR phosphorylation in breast cancer is very limited; however, the post-translation status in conjunction with localization of AR deserves more research as studies suggest it may be a novel indicator of breast cancer progression in certain subtypes." (PMID 30416486, 2018).
breast carcinoma (continued). "Therefore, we assessed AR gene expression in 925 breast cancers cases within the TCGA dataset." (PMID 29912871, 2018). "However, several inconsistencies exist within the literature as to which subtypes of breast cancer express AR or whether it can be used to define its own unique subtype." (PMID 30279965, 2018). "In addition, AR could inhibit tumorigenesis and metastasis of ER+ breast cancer cells in the serial xenotranplanted animal models." (PMID 29423076, 2018). "Steroid levels are known to be altered by lifestyle factors such as diet and exercise; understanding their potential role in dictating the function of AR in breast cancer development could therefore have wide-ranging effects in prevention and treatment of this disease." (PMID 30416486, 2018). "On the other hand, they also found that AR expression in ER-negative TNBC breast cancers was significantly associated with increased mortality, as compared with AR-negative, ER-negative TNBC tumors (multivariate hazard ratio (model 3), 1.83; 95 percent confidence interval, 1.11 to 3.01; p = 0.02)." (PMID 30314329, 2018). "Additionally, loss of AR was independent of other hormone receptors, such as ER and PR, and was associated with an earlier time of breast cancer diagnosis (3 years earlier than AR-positive patients and 6 years earlier for AA patients)." (PMID 29912871, 2018). "Women with Ki67 expression above the median had suggestively higher risk of breast cancer, irrespective of AR expression (low AR/high Ki67: OR = 1.5, 95% CI = 0.6–3.9; high AR/high Ki67: OR = 1.2, 95% CI = 0.5–3.1), relative to women with low AR and low Ki67 expression." (PMID 30276234, 2018). "This might indicate a better endocrine sensitivity of AR-expressing breast cancer." (PMID 30577860, 2018). "As AR expression is retained in a number of metastatic breast cancers understanding the functional implication of its expression at different stages of the disease could provide the opportunity for more effective use of anti-AR stage tailored therapies." (PMID 30416486, 2018). "Thus, AR could be used as a prognostic marker for breast cancer, particularly in AA “QNBC” patients." (PMID 29912871, 2018). "We suppose that AR, let-7a and BT-IC may affect the progression of breast cancer together." (PMID 29423076, 2018). "There are several mechanisms by which AR may activate HER2 in HER2 + breast cancer cells." (PMID 29109513, 2017). "Indeed, if more generalizable, anti-androgen therapy may be a potentially effective treatment for all women with AR-positive breast cancer with limited added toxicity." (PMID 28840192, 2017). "Importantly, the identified AR co-expressed genes are likely to include biologically significant AR target genes and transcriptional coregulators that are present across different subtypes of breast cancer." (PMID 28915724, 2017). "We also encourage further research to identify novel genes and pathways, which were not previously reported to induce breast cancer; and AR-regulated lincRNA, lncRNA and miRNAs (miRTarBase web tool) which may cause breast cancer in post-menopausal women." (PMID 29254284, 2017). "The expression of the androgen receptor (AR) plays various different prognostic roles depending on the breast cancer subtype, such as the difference between ER-positive and ER-negative breast cancers with the expression levels of around 67–88% and 12–50% for AR, respectively." (PMID 28299476, 2017). "Interestingly, many pre-clinical studies show differing proliferative versus anti-proliferative effects in ERα and AR-positive breast cancer that correlates with variation in the ratio of these steroid receptors and the availability of their respective ligands (i.e., estradiol and DHT)." (PMID 28245550, 2017).
breast carcinoma (continued). "While most hormonal-based therapies for breast cancer involve inhibiting estrogen receptor (ER)-signaling in hormone receptor positive subtypes, it has recently come to light that AR-signaling is likely an important modulator of breast cancer cell survival and may also be a viable target." (PMID 28085048, 2017). "However, a recent ChIP-seq study of ER binding sites demonstrated that treatment of MCF-7 breast cancer cells with the AR antagonist enzalutamide decreased the number of E2-induced ER genomic binding sites by 50%, implicating a role for AR in ER genomic binding." (PMID 29254284, 2017). "The AR could serve as an independent prognostic factor for DFS of ERα-positive breast cancer." (PMID 28474005, 2017). "However, the role of AR in breast cancer needs to be more investigated." (PMID 28957377, 2017). "Therefore, this differential pattern of AR expression can explain a relatively higher expression of C1orf64 observed in ER-positive compared to ER-negative tumors and at the same time a strong correlation between AR and C1orf64 expression across all breast cancer subtypes." (PMID 28915724, 2017). "In addition, role of AR in breast cancer is not fully understood." (PMID 28474005, 2017). "Therefore, in a similar way, C1orf64 may have a function in mediating the activities of AR inhibitors in breast cancer." (PMID 28915724, 2017). "In this respect, a plausible hypothesis is that C1orf64, in turn, may have a negative regulatory effect on AR function in breast cancer, which would provide a biological advantage for AR to repress C1orf64 expression in order to sustain its own transcriptional activity." (PMID 28915724, 2017). "Furthermore, there is a functional interplay between AR and C1orf64 in breast cancer." (PMID 28915724, 2017). "Although the importance of AR in breast cancer has been challenged, there is sufficient evidence that its action in ERα-negative breast cancer may involve increase in cell proliferation and anti-apoptosis, steps that lead to poor outcomes from cancer treatment." (PMID 28474005, 2017). "Importantly, there is a functional interplay between AR and C1orf64 in breast cancer cells." (PMID 28915724, 2017). "In fact, although the luminal androgen receptor subtype of breast cancer was the focus of these studies, AR is known to be more highly expressed in ER-positive breast cancers, including luminal B subtype cancers, and may represent a novel and effective treatment opportunity in these patients." (PMID 28840192, 2017). "Previous research on AR expression in BC reported that AR expression was positively correlated with ER expression and only affected ER-positive breast cancer." (PMID 28060723, 2017). "Recent report suggested that HR-negative BC was categorized based on AR pathway activation and AR-activated HR-negative breast cancer showed a proliferative response to androgens without ER dependence." (PMID 28060723, 2017). "By inducing immunogenic modulation in AR- breast carcinomas, particularly by reducing OPG expression, enzalutamide may not only provide monotherapy efficacy in this patient population but also could further impact TNBC patient care if combined with cancer immunotherapy." (PMID 27015557, 2016). "For instance, AR is starting to be recognized as attractive target in triple-negative (ER-/PR-/Her2-) breast cancer and may be a critical target in other human malignancies in which sex differences exist in incidence and mortality, such as bladder cancer and hepatic cell carcinoma." (PMID 26876983, 2016). "Additionally, high levels of AR relative to ER may also pinpoint a subset of breast cancers patients that would respond more favorably to enzalutamide alone or in combination with TAM or AIs." (PMID 27548161, 2016). "However, clinical data supporting the hypothesis is unconvincing, AR has been reported as a favorable prognostic factor in ER+ breast cancer, but its prognostic value remains controversial in ER− tumors." (PMID 27285752, 2016).
breast carcinoma (continued). "In addition, expression of the androgen receptor (AR) has also been frequently noted, suggesting that androgens may also play a role in breast cancer biodynamics." (PMID 26757422, 2016). "Given the arrival of AR-targeting agents to the breast cancer clinical arena, the heterogeneous nature of this disease and the dichotomous actions of AR in different breast cancer contexts, the question of whether AR-Vs are expressed in breast malignancies is critically important." (PMID 26554309, 2015). "Breast cancer cell lines may be at least AR-dependent [S116, S117]." (PMID 25595907, 2015). "Moreover the effects of DHT on cell proliferation and apoptosis are reversed by the treatment of breast cancer cells with bicalutamide and we propose that it might be useful in the chemotherapy of TNBCs, which are positive for downstream AR signalling." (PMID 25781993, 2015). "Moreover, BRCA1-related breast cancer is associated with a basal-like phenotype in which EGFR is a basal marker and approximately one in five BRCA1 mutated breast cancers which were negative for ER and PR expressed AR." (PMID 25695063, 2015). "In this study, we examined the effect of enzalutamide in AR + breast cancer models (ER + and ER–) and present the first preclinical evidence that inhibition of AR with enzalutamide may be an effective therapeutic strategy not only for ER–/AR + breast cancers, but also for ER+/AR + tumors." (PMID 24451109, 2014). "Hence, investigating the relationship between AR CAG repeats and breast cancer susceptibility may provide direct insight into the relationship between AR activity and breast cancer susceptibility in humans." (PMID 25928046, 2014). "AR to ER ratio may influence breast cancer response to traditional endocrine therapy." (PMID 24451109, 2014). "Besides, androgen receptor could up-regulate miR-19a and androgen receptor positive breast cancer has relatively low chemosensitivity." (PMID 25137071, 2014). "Estrogens can bind to ERs and contribute to the growth of breast cancer, and androgens may act directly, promoting cellular growth and proliferation via binding to the androgen receptor, or indirectly, via their aromatization to estrogens, either peripherally or in breast tissue." (PMID 24915186, 2014). "Indeed, AR and ER can directly interact in breast cancer cells." (PMID 24451109, 2014). "We suggest that induction of ER beta expression by mibolerone may play a critical regulatory role in ER-positive cells, addressing prospectively that combined agents able to potentiate ER beta and AR signalings may be useful to inhibit breast cancer cell growth and progression." (PMID 24552459, 2014). "Thus, in breast cancer AR is a negative regulator of L1CAM expression." (PMID 25510351, 2014). "In vitro studies have demonstrated that androgen signaling may counteract the proliferative effect of estrogens in AR-positive breast cancer cells, while over-expression of the AR markedly decreases ER alpha transcriptional activity in ER-positive breast cancer cells." (PMID 24552459, 2014). "AR signaling effects on breast cancer progression may depend on ERα and ERBB2 status." (PMID 23593223, 2013). "Moreover, in ER positive breast cancer patients, the expression of AR could predict better OS (HR 0.39, 95% CI 0.19-0.82)." (PMID 24324816, 2013). "Hence, there is no consensus on the association between AR expression detected by IHC and good survival in patients with breast cancer." (PMID 24324816, 2013). "This suggests that the AR may have a tumor-suppressive effect in breast cancer cells." (PMID 24403250, 2013). "Androgens and AR may have some important roles in breast cancer." (PMID 24324816, 2013). "The expression of AR could also predict better OS in patients with ER positive breast cancer." (PMID 24324816, 2013).